ESRRG (estrogen related receptor gamma)
Description:
Orphan receptor that acts as a transcription activator in the absence of bound ligand. Binds specifically to an estrogen response element and activates reporter genes controlled by estrogen response elements (By similarity). Induces the expression of PERM1 in the skeletal muscle.
Synonyms: ERR3; NR3B3; ERRg; ERR-gamma; ERRgamma
Tractability: Small molecule: a drug acting on it is in phase 2 or 3 trials; a structure with a bound ligand is known; a high-quality ligand is known; it has a high-quality binding pocket; it belongs to a druggable protein family. PROTAC: UniProt records ubiquitination sites on it; ubiquitination databases record sites on it; a small molecule that binds it is known.
Target class: Nuclear hormone receptor subfamily 3; Transcription factor; Nuclear receptor; Nuclear hormone receptor subfamily 3 group B member 3; Nuclear hormone receptor subfamily 3 group B
Gene: Protein-coding gene on chromosome 1 (216,503,246 to 217,137,755, reverse strand). Ensembl gene ENSG00000196482.
Subcellular location: Nucleus
Subcellular location (Human Protein Atlas): Nucleoplasm
Pathways (Reactome):
Gene expression (Transcription): Nuclear Receptor transcription pathway
Gene Ontology:
Molecular function: protein binding; sequence-specific double-stranded DNA binding; AF-2 domain binding; DNA-binding transcription factor activity, RNA polymerase II-specific; estrogen response element binding; nuclear receptor activity; DNA binding; DNA-binding transcription activator activity, RNA polymerase II-specific; DNA-binding transcription factor activity; nuclear steroid receptor activity; RNA polymerase II transcription regulatory region sequence-specific DNA binding; sequence-specific DNA binding; steroid binding; zinc ion binding
Biological process: regulation of DNA-templated transcription; positive regulation of cold-induced thermogenesis; positive regulation of transcription by RNA polymerase II; regulation of transcription by RNA polymerase II; nuclear receptor-mediated steroid hormone signaling pathway; positive regulation of DNA-templated transcription; retinoic acid receptor signaling pathway
Cellular component: chromatin; nucleoplasm; nucleus
Genetic constraint (gnomAD): Loss-of-function variants: 9 observed, 33.87 expected, observed/expected ratio (o/e) 0.27, 90% interval 0.16 to 0.46. The upper end of that interval is the gene's LOEUF score, 0.46, which puts it in group 2 of 6, group 1 being the genes least tolerant of losing a copy. Missense variants: 362 observed, 537.59 expected, observed/expected ratio (o/e) 0.67, 90% interval 0.62 to 0.74. Synonymous variants: 198 observed, 205.68 expected, observed/expected ratio (o/e) 0.96, 90% interval 0.86 to 1.08.
Homologues: Orthologues: mouse Esrrg (100% identical), pig ESRRG (99% identical), guinea pig ESRRG (99% identical), dog ESRRG (98% identical), rabbit ESRRG (97% identical), chimpanzee ESRRG (96% identical), macaque ESRRG (96% identical), rat Esrrg (96% identical), tropical clawed frog esrrg (93% identical), zebrafish esrrga (90% identical), Drosophila melanogaster ERR (41% identical). Paralogues in human: ESRRB (76% identical), ESRRA (55% identical), ESR1 (35% identical), ESR2 (33% identical), NR3C2 (27% identical), PGR (26% identical), NR3C1 (26% identical), AR (24% identical).
Diseases named in the same sentence as ESRRG in open-access papers:
ESRRG is named in the same sentence as 119 diseases in open-access papers, as found by Europe PMC text mining. Sharing a sentence is not in itself a finding about the gene and the disease. The quoted sentences say what the papers report.
breast carcinoma (41 papers, 2012 to 2025). "High expression of ESRRG has been associated with a favorable clinical prognosis in both ovarian and breast cancers." (PMID 37679788, 2023). "Inhibition of ESRRG expression in breast cancer cells significantly downregulated three carboxylic acid-related genes." (PMID 37679788, 2023). "It was reported that ESRRG, a transcriptional activator, regulated the proliferation of breast cancer cells by directly binding to the response element in the promoter of DNA cytosine 5-methyltransferase 1 (DMNT1)." (PMID 36612032, 2022). "Estrogen-related receptor gamma (ERR-γ) and ERβ increase positive estrogen-like influences in the prostate, and ERR-γ has been shown to slow proliferation in prostate and breast cancer cell lines." (PMID 35847835, 2022). "Estrogen-related receptor gamma is a tumor suppressor as well as an activator of multiple cancers, including gastric cancer, breast cancer, laryngeal squamous cell carcinoma, and liver cancer." (PMID 33193574, 2020). "Estrogen-related receptor gamma (ESRRG, ERRγ) is an orphan nuclear receptor with broad, structural similarities to classical ER that is widely implicated in the transcriptional regulation of energy homeostasis; in breast cancer, ERRγ is preferentially expressed in ER+ disease." (PMID 25971350, 2015). "In breast cancer cells, a high level of miR-378* induces the metabolic shift from an oxidative to a glycolytic bioenergetics pathway by inhibiting the expression of two PGC-1β partners, ERRγ (estrogen-related receptor gamma) and GABPA (GA binding protein transcription factor, alpha subunit)." (PMID 29445084, 2018). "ERRγ signaling is associated with poor DMFS in ER+, TAM-treated breast cancer, and ESRRG, EEF1A2, and PPIF comprise a 3-gene signaling node that may contribute to TAM resistance in the context of an active ERK/MAPK pathway." (PMID 25971350, 2015). "In addition, miR-378 affects the TCA cycle in breast cancer by modulating the expression of peroxisome proliferator-activated receptor-alpha, GA binding protein transcription factor, subunit (GABPA), co-activator 1-alpha (PGC-1α), and estrogen-related receptor gamma (ERRγ)." (PMID 36483029, 2022).
prostate carcinoma (23 papers, 2013 to 2025). A carcinoma that arises from epithelial cells of the prostate gland. "Although no studies have yet reported on COL10A1, ADA, or LHFP and cancer survival, CTSB and MMP9 have both been previously associated with survival in gastric cancer, while ESRRG expression has been associated with survival in prostate cancer." (PMID 23717493, 2013). "Estrogen-related receptor gamma (ERR-γ) decreases the rate of proliferation and slows the progression rate of prostate cancer." (PMID 35847835, 2022). "Mechanism analyses have revealed that ESRRG plays a key role in fatty acid oxidation and suppresses proliferation of both androgen-sensitive and -insensitive prostate cancer cell via the induction of p21WAF1/CIP1 and p27KIP1." (PMID 32571331, 2020). "Downregulation of ESRRG has been found in certain types of prostate carcinomas, and it has been shown that its increased expression can repress tumor proliferation regardless of androgen sensitivity." (PMID 29740534, 2018). "ESRRG suppress cell proliferation in prostate cancer cells and the estrogen receptor beta agonist diarylpropionitrile (DPN) exhibit a pro-apoptotic and anti-proliferative effect on MB." (PMID 24093088, 2013). "Several researchers have proposed that ESRRG may be a potential therapeutic target for gastric and prostate cancers." (PMID 37679788, 2023). "The ESRRG-specific agonist DY131 has been found to suppress gastric carcinoma and prostate cancer cell proliferation." (PMID 37679788, 2023). "Additionally, the presence of estrogen-related-receptor gamma (ERR-γ) appears to play an important role in prostate health, where it has been shown to slow proliferation/growth in androgen-sensitive prostate cancer cells." (PMID 36982560, 2023).
gastric cancer (15 papers, 2013 to 2025). A primary or metastatic malignant neoplasm involving the stomach. "In conclusion, three hub genes (ATP4A, ATP4B, and ESRRG) closely related to gastric cancer were mined, based on which the ML diagnostic model of gastric cancer was conducted." (PMID 35812327, 2022). "For example, ESRRG has been shown to antagonize the proliferation of gastric cancer cells by suppressing TCF4/LEF1 binding to the CCND1 promoter, highlighting its tumor suppressor role." (PMID 37679788, 2023). "TFF1 is a well-known tumor suppressor in gastric cancer (GC) and a downstream target of the nuclear receptor estrogen-related receptor gamma." (PMID 36917092, 2023). "ESRRG has been identified as a candidate tumor suppressor gene in gastric cancer that can inhibit Wnt signaling via the suppression of transcription factor 4 (TCF4)/lymphoid enhancer-binding factor 1 (LEF1), binding to the Cyclin D1 (CCND1) promoter." (PMID 37240447, 2023). "Our data thus demonstrated that Sophoridine depends on ESRRG to induce β-catenin degradation and which contributes to its tumor suppressive properties in gastric cancer cells." (PMID 32571331, 2020). "Sophoridine depends on targeting ESRRG/β-catenin pathway to exert tumor-suppressive activities in gastric cancer cells and enhances the anti-tumor effect of cisplatin." (PMID 32571331, 2020). "As a member of nuclear receptors (NR) superfamily of transcription factors, ESRRG has been identified as a tumor suppressor and an attractive therapeutic target in human breast, thyroid, prostate, endometrial and gastric cancers." (PMID 32571331, 2020). "Here the authors show estrogen-related receptor gamma (ESRRG) is a tumor suppressor in gastric cancer and suggest the mechanism of this tumor suppression function involves the inhibition of Wnt signaling." (PMID 29765046, 2018). "ESRRG is an important tumor suppressor in human breast, endometrial, prostate and gastric cancer, we next investigated whether ESRRG is required for the anti-tumor activities of Sophoridine in gastric cancer cells." (PMID 32571331, 2020).
hepatoma (14 papers, 2012 to 2025). "An orally inverse agonist of ESRRG promotes ferroptosis in sorafenib-resistant hepatocellular carcinoma." (PMID 40356747, 2025). "In hepatocellular carcinoma, high ESRRG expression correlates with increased tumor aggressiveness and poor clinical outcomes." (PMID 40356747, 2025). "In hepatoma cell line, expression of estrogen-related receptor gamma (ERRγ), a regulator of mitochondrial function, has been enhanced by ATF6α and PGC1α." (PMID 33525374, 2021). "Additionally, antagonizing ESRRG triggers ferroptosis in sorafenib-resistant hepatocellular carcinoma." (PMID 40356747, 2025). "In addition, in hepatoma cell lines, ATF6 and PGC-1α activities enhance estrogen-related receptor gamma (ERRγ) expression." (PMID 35225153, 2022). "Moreover, the Estrogen-Related Receptor Gamma (ESRRG) was targeted by miR-940, and suppression of ESRRG inhibited hepatocellular carcinoma cell lines growth and induced cell apoptosis." (PMID 28423620, 2017).
Obesity (11 papers, 2012 to 2022). Accumulation of substantial excess body fat. "However, recent studies have disclosed different receptors such as androgen receptor, GPR30, glucocorticoid receptor, and estrogen-related receptor gamma (ERRγ) have been hypothesized linked to obesity in association with BPA action." (PMID 35328389, 2022).
liver cancer (9 papers, 2018 to 2026). An epithelial or non-epithelial malignant neoplasm that arises from the liver. "Conversely, liver cancer, showing high levels of ESRRG immunoreactivity, was found to be associated with advanced tumor node metastasis, at a late stage and of a high grade, which correlated with poorer overall survival." (PMID 37240447, 2023). "Further, significant rising expression levels of ESRRG from T1 to T3 stage of liver cancer tissues were observed, implying an increasing tendency of ESRRG expression during malignant transformation." (PMID 32206097, 2020). "The ESRRG gene (encoding estrogen related receptor gamma) was identified as a 5hmC marker component of a cfDNA-based diagnostic model for early HCC, according to our previously published research on the 5hmC biomarker discovery in liver cancer." (PMID 37387524, 2023). "In liver cancer, however, ESRRG appears to exert oncogenic potential by suppressing p21 and p2726." (PMID 29765046, 2018).
endometrial cancer (7 papers, 2021 to 2025). Primary or metastatic malignant neoplasm involving the endometrium (mucous membrane that lines the endometrial cavity). "In endometrial cancer, it targets tumor suppressors PTEN and ESRRG to inhibit apoptosis and drive proliferation." (PMID 39744510, 2025).
breast tumors (6 papers, 2009 to 2024). "Interestingly expression of ESRRG is also significantly associated with a reduction in pathologic complete response (pCR) in locally advanced breast tumors treated with chemotherapy." (PMID 25971350, 2015). "In addition, ESRRA was downregulated in breast tumors but upregulated in the other tumors, and ESRRB and ESRRG were upregulated in breast, ovarian, and endometrial tumors." (PMID 38582811, 2024).
ovarian carcinoma (5 papers, 2021 to 2023). A malignant neoplasm originating from the surface ovarian epithelium. "Additionally, this research provides the first in silico study on ESRRG’s involvement in ovarian cancer." (PMID 36829472, 2023). "In contrast to the chemerin protein data from IHC, mRNA levels of the RARRES2 gene in ovarian cancer were not correlated with PGR, ESR2, ESRRA, ESRRB, ESRRG, nor CEACAM5 after analysis of both patient collectives on the mentioned platforms (p > 0.05 for all)." (PMID 36900088, 2023).
preeclampsia (5 papers, 2018 to 2024). Preeclampsia is a hypertensive disorder of pregnancy that is characterized by new-onset hypertension with proteinuria presenting after 20 weeks of gestation, and depending on mild or severe forms may initially present with severe headache, visual disturbances, and hyperreflexia. "ESRRG was identified as a hub for the late-stage network, and abnormal reduction of ESRRG expression in human placenta is associated with intrauterine growth restriction and preeclampsia." (PMID 31596842, 2019). "ESRRG is highly expressed in the human placenta, and its reduced expression is possible to be involved in fetal growth restriction and preeclampsia." (PMID 36830409, 2023). "Early-onset preeclampsia may be driven by placental dysfunction, which occurs when a placental abnormality restricts blood flow, potentially due to suppression of estrogen-related receptor-gamma leading to vascular abnormalities." (PMID 38630528, 2024). "Predominantly placenta-expressed genes, down-regulated in module M1, are regulators of fetal growth (CSH1, HSD11B2), metabolism (ESRRG), estrogen synthesis (HSD17B1), and immune functions (LGALS14), some of which were reported to be down-regulated in preeclampsia." (PMID 30135684, 2018).
type 2 diabetes (5 papers, 2013 to 2024). "mir-433 (fold change of −9,6) is activated by the estrogen receptor ESRRG, in which several SNPs have been associated with higher risk of type 2 diabetes by GWAS and that acts as a co-activator of the demethylating enzyme Dnmt1." (PMID 23335998, 2013).
cardiac hypertrophy (4 papers, 2020 to 2025). "Additionally, scGO identified genes such as ZBTB20, ESRRG, and SOX6, which have established links to the onset of cardiac hypertrophy." (PMID 39820437, 2024).
anaplastic thyroid cancer (3 papers, 2017 to 2023). "Previously, we reported that an inverse agonist of estrogen-related receptor gamma (ERRγ), GSK5182, enhances sodium iodide (Na+/I−) symporter (NIS) function through mitogen-activated protein (MAP) kinase signaling in anaplastic thyroid cancer cells." (PMID 36766812, 2023).
esophageal squamous cell carcinoma (3 papers, 2023 to 2025). Esophageal squamous cell carcinoma (ESCC) is a type of esophageal carcinoma (EC) that can affect any part of the esophagus, but is usually located in the upper or middle third. "Our study has uncovered the significant roles and underlying mechanisms of ESRRG in regulating the proliferation and metabolism of esophageal squamous cell carcinoma (ESCC)." (PMID 37679788, 2023). "In this study, we investigated the role of estrogen-related receptor gamma (ESRRG) in metabolic reprogramming in esophageal squamous cell carcinoma (ESCC)." (PMID 37679788, 2023). "In esophageal squamous cell carcinoma, the administration of the estrogen-related receptor gamma(ESRRG) specific agonist DY131 downregulate PKM2 expression with a marked suppression of glycolytic activity and lactate production, synergistically augmenting the efficacy of anti-PD-1 treatment." (PMID 39897050, 2025). "To investigate the role of ESRRG in esophageal squamous cell carcinoma (ESCC), we analyzed its expression in various datasets, including TCGA-ESCC, GSE38129, and GSE53625." (PMID 37679788, 2023).
injury (3 papers, 2019 to 2024). Damage inflicted on the body as the direct or indirect result of an external force, with or without disruption of structural continuity. "In this study, we report that carbon tetrachloride (CCl4)-induced acute liver injury upregulates hepatic estrogen-related receptor gamma (ERRγ) and FGF23 gene expression and FGF23 secretion from liver." (PMID 37396546, 2023).
migraine (3 papers, 2021 to 2023). "Moreover, a genome-wide association study (GWAS) of the Han Chinese population revealed that rs146094041 in ESRRG and rs7124169 in chromosome 11 were more susceptible to early-onset migraine." (PMID 37305749, 2023).
thyroid cancer (3 papers, 2020 to 2023). "DN200434, the recently discovered orally bioavailable agonist of ESRRG, enhanced radioiodine therapy responsiveness in thyroid cancer with either KRAS or BRAF mutations both in vitro and in vivo." (PMID 32571331, 2020).
gallbladder cancer (2 papers, 2020 to 2025). "Overall, ESRRG is a promising therapeutic target in gallbladder cancer and other biliary tract tumors." (PMID 40356747, 2025). "ESRRG expression was analyzed through immunohistochemical staining in gallbladder cancer and cholecystitis tissues." (PMID 40356747, 2025). "Lastly, guided by the pan-cancer analysis, we validated the impact of ESRRG on proliferation, migration, invasion, and PD-L1-mediated immune evasion in gallbladder cancer." (PMID 40356747, 2025). "Summarizing the results from our pan-cancer analysis, we have identified ESRRG as a pivotal factor in the progression of biliary tract tumors, including gallbladder cancer." (PMID 40356747, 2025). "Knockdown of ESRRG in gallbladder cancer cells results in decreased proliferation, migration, and invasion." (PMID 40356747, 2025). "The purpose of our research is to explore the commonalities and underlying mechanism of ERRs in malignancies from a pan-cancer perspective and to validate the role and mechanisms of ESRRG in gallbladder cancer (GBC)." (PMID 40356747, 2025). "In order to get more insight into the function of ESRRG in CHOL represented by gallbladder cancer, we performed validation studies on both cells and tissues." (PMID 40356747, 2025). "Our findings demonstrate that ESRRG knockdown in gallbladder cancer cells significantly impairs cell proliferation and migration, accompanied by a decrease in key elements of the EMT, MAPK, and mTOR signaling pathways." (PMID 40356747, 2025). "In summary, these results suggest the importance of ESRRG in facilitating the growth, migration, and invasion of gallbladder cancer cells." (PMID 40356747, 2025). "And it also implies that ESRRG may be an oncogenic component in the pathogenesis of gallbladder cancer." (PMID 40356747, 2025). "Given the homology between ERR family members (including ESRRG) and estrogen receptors, ESRRG may influence gallbladder cancer progression via involvement in estrogen signaling pathways, a hypothesis that merits further exploration." (PMID 40356747, 2025). "Furthermore, our study revealed that ESRRG promotes the progression of gallbladder cancer via inhibiting tumor immune microenvironment and, notably, for the first time, demonstrated a positive correlation between ESRRG expression and PD-L1 expression in gallbladder cancer." (PMID 40356747, 2025).
Hearing impairment (2 papers, 2021 to 2023). A decreased magnitude of the sensory perception of sound. "The ESRRG expression is highly upregulated in cochlear hair cells and linked to a candidate gene for senile hearing impairment." (PMID 37305749, 2023).